IL17A (interleukin 17A)
Diseases named in the same sentence as IL17A in open-access papers (continued):
Sharing a sentence is not in itself a finding about the gene and the disease.
psoriatic arthritis (335 papers, 2008 to 2026). Joint inflammation associated with psoriasis. "Ixekizumab, an IL-17A inhibitor, is commonly used to treat moderate-to-severe plaque psoriasis and psoriatic arthritis, with a well-documented risk of mucocutaneous Candida infections, though its role in bacterial infections is less defined." (PMID 40917923, 2025). "The selective blockade of IL-17A through secukinumab or ixekizumab, causing a simultaneous neutralization of IL-17AA homodimers and IL-17AF heterodimers, has shown a fast and constant efficacy in the treatment of plaque-type psoriasis, nail psoriasis and psoriatic arthritis." (PMID 36614836, 2022). "For that purpose, we conducted a comprehensive literature search on PubMed for studies published between 2007 and 2025, using keywords such as “bimekizumab”, “IL-17”, “IL-17A”, “IL-17F”, “psoriatic arthritis”, and “ankylosing spondylitis”." (PMID 40076933, 2025). "BACKGROUND: Ixekizumab, an interleukin 17A inhibitor, has demonstrated efficacy in improving clinical and patient-reported outcomes in axial spondyloarthritis (axSpA) and psoriatic arthritis (PsA)." (PMID 41102851, 2025). "In the double-blind, placebo-controlled phase 2 ARGO trial, patients with active psoriatic arthritis treated with a nanobody targeting IL-17A and IL-17F showed substantially better disease response rates compared with those receiving placebo treatment." (PMID 41053449, 2025). "Previously IL-17A and IL-17A-producing cells have been identified to affect focal inflammation, structural damage and new bone formation in psoriatic arthritis and ankylosing spondylitis." (PMID 40138866, 2025). "Ixekizumab, an IL-17A antagonist, is a biologic therapy approved for moderate to severe plaque psoriasis and psoriatic arthritis." (PMID 40917923, 2025). "Secukinumab is a monoclonal antibody targeting interleukin-17A (IL-17A), approved for the treatment of moderate-to-severe plaque psoriasis and psoriatic arthritis." (PMID 40757116, 2025). "Secukinumab (SECU) is a promising fully human anti-IL-17 monoclonal antibody that selectively neutralizes IL-17A, approved for the treatment of moderate to severe plaque psoriasis, psoriatic arthritis and ankylosing spondylitis." (PMID 38543124, 2024). "IL-17A+ CD8+ T cells have been identified in the synovial tissue of psoriatic arthritis patients and have been shown to induce pro-inflammatory responses in synovial fibroblasts." (PMID 38672170, 2024). "Elevated levels of Th17 cells and IL-17A have been detected in skin lesions, blood, and synovial fluid from patients with psoriatic arthritis (PsA) and ankylosing spondylitis (AS)." (PMID 38292069, 2024). "Secukinumab (SECU) is a fully human anti-IL-17 monoclonal antibody approved for treatment of moderate to severe plaque psoriasis, psoriatic arthritis, and ankylosing spondylitis for its ability to selectively neutralize IL-17A." (PMID 39062111, 2024). "Among these, secukinumab, a fully human IL-17A monoclonal antibody, has been sanctioned for the management of plaque psoriasis, psoriatic arthritis, ankylosing spondylitis, among other conditions." (PMID 39219794, 2024). "Overall, immunohistochemical reactivity for TGF-β1 in synovial tissue was elevated in patients with psoriatic arthritis (p = 0.024) and was positively correlated with IL-17A (r = 0.355, p = 0.024) and Dkk1 (r = 0.444, p = 0.004)." (PMID 38672170, 2024). "In connective tissue diseases, IL-17A and IL-17A-producing cells have been demonstrated to influence focal inflammation, structural damage as well as new bone formation in psoriatic arthritis and ankylosing spondylitis." (PMID 38587715, 2024). "In mouse models of chronic IL-17A-mediated skin inflammation, which mimics the psoriatic arthritis, IL-17 from γδ T cells, ILCs and keratinocytes negatively regulated osteogenesis by suppressing the Wnt signaling." (PMID 39060500, 2024).
psoriatic arthritis (continued). "In patients with psoriatic arthritis, high levels of IL-23 and IL-17A are present in the synovium, and tissue-retained Th17 cells highly express IL-22 and IL-17A." (PMID 37920459, 2023). "We aimed in this study to evaluate the impact of maternal interleukin -17A and the activity of the illness on pregnancy outcomes in Psoriatic arthritis (PsA) and ankylosing spondylitis (AS) patients." (PMID 36650451, 2023). "Patients with psoriatic arthritis often have resident Th17 cells within the synovium that overexpress IL-17A and IL-22, exacerbating inflammation and bone reconstruction." (PMID 37920459, 2023). "The pan-BET bromodomain HAT inhibitor (JQ1) reduced the ratio of IL17A+/IFNY+ T cells and IL17A secretion in both psoriatic arthritis patients and healthy individuals." (PMID 37833997, 2023). "Ixekizumab is a monoclonal antibody targeting IL-17A with efficacy and safety profiles similar to secukinumab in the treatment of skin psoriasis and psoriatic arthritis." (PMID 35861513, 2023). "The first case report of successful GCA treatment with a monoclonal antibody against IL-17A (secukinumab) appeared in 2018 in a patient with additional psoriatic arthritis, in which secukinumab is approved for therapy." (PMID 38299156, 2023). "Secukinumab, a fully human monoclonal antibody targeting IL-17A, is approved for the treatment of autoimmune psoriasis, psoriatic arthritis (PsA), and ankylosing spondylitis (AS)." (PMID 36983699, 2023). "Secukinumab is a fully human monoclonal antibody targeting IL-17A which has been approved for the treatment of autoimmune psoriasis, psoriatic arthritis (PsA), and AS." (PMID 36983699, 2023). "In vitro -induced IL-17A+ CD8+ T-cells increase the production of proinflammatory cytokines from psoriatic arthritis synovial fibroblasts; this was reduced by IL-17A and TNFα blockade." (PMID 37367825, 2023). "Immunotherapeutics for targeting IL-17A have been developed for the treatment of RA and psoriatic arthritis (PsA)." (PMID 35874732, 2022). "Below, we will review the role of the IL-23/IL-17 axis in the pathology of AxSpA including ankylosing spondylitis and psoriatic arthritis with a particular focus on IL-17A and IL-17F." (PMID 35861937, 2022). "Nonetheless, neutralization of IL-17A is an established treatment in patients with psoriatic arthritis and axial spondylarthritis." (PMID 35874732, 2022). "In this study, we show that IL-17A, a cytokine important in arthritic pathologies such as RA and psoriatic arthritis (PsA), also has a role in alphavirus-induced musculoskeletal immunopathology." (PMID 35254128, 2022). "For example, secukinumab, which selectively inhibits IL-17A, has now been approved for the treatment of moderate-to-severe plaque psoriasis, ankylosing spondylitis, and psoriatic arthritis." (PMID 33205383, 2021). "Ixekizumab is a humanized anti-IL-17A antibody that has shown similar efficacy for psoriasis and psoriatic arthritis." (PMID 34993035, 2021). "Secukinumab is a fully humanized monoclonal antibody against IL-17A, and it is effective in the treatment of plaque psoriasis, psoriatic arthritis, and ankylosing spondylitis." (PMID 34993035, 2021). "Psoriatic arthritis and ankylosing spondylitis in particular have been found to be clinically responsive to anti–IL-17A treatment." (PMID 34544860, 2021). "For example, TNFα-, IL-6R- and IL-1β-neutralizing bDMARDs work in RA, whereas IL-17A and IL-12/23-neutralizing bDMARDs are very efficient in psoriatic arthritis or spondyloarthritis." (PMID 34680530, 2021). "Given the higher efficacy of anti-IL-17A in psoriatic arthritis, it would be of great interest to study differences in the induction of the pro-inflammatory feedforward loop by the CCR6+ memTh subpopulations between RA and PsA patients in future studies." (PMID 34082814, 2021).
psoriatic arthritis (continued). "High levels of Th17 cells have been found in psoriatic synovial fluid compared to rheumatic synovial fluid, similarly, high levels of IL-17A have been found in the synovial fluid and synovial membrane of patients with psoriatic arthritis." (PMID 34829740, 2021). "There is an FDA approved anti-IL-17A drug that is currently being administered to patients by intravenous injections for treatment of plaque psoriasis, psoriatic arthritis, and ankylosing spondylitis." (PMID 32429598, 2020). "Ixekizumab is another mAb specific for IL-17A that is approved for the treatment of moderate-to-severe plaque psoriasis and active psoriatic arthritis." (PMID 32398096, 2020). "Secukinumab (Cosentyx), a fully-human monoclonal antibody that acts by selectively binding to and neutralising the proinflammatory cytokine IL-17A, is used widely for the treatment of both chronic plaque psoriasis and psoriatic arthritis." (PMID 32774388, 2020). "Resolution of synovitis and arrest of catabolic and anabolic bone changes in patients with psoriatic arthritis by IL-17A blockade with secukinumab: results from the prospective PSARTROS study." (PMID 33195301, 2020). "IL-17A is a known driver in many inflammatory diseases affecting bone, e.g. ankylosing spondylitis (AS), psoriatic arthritis (PsA) and RA." (PMID 32231224, 2020). "Although the effects of interleukin-17A (IL-17A) inhibition on the signs and symptoms of psoriatic arthritis (PsA) are well defined, little is known about its impact of local inflammatory and structural changes in the joints." (PMID 30053825, 2018). "Fully human monoclonal antibody ixekizumab (Taltz) by Eli Lilly and Co., blocking IL-17A-mediated signaling, is approved for treatment of moderate-to-severe forms of plaque psoriasis and psoriatic arthritis." (PMID 30304852, 2018). "Subsequently, similar positive efficacy for inhibition of IL-17A was seen in patients with ankylosing spondylitis and psoriatic arthritis." (PMID 28270233, 2017). "More recently, it was shown that IL-17A+ CD8+ T cells are enriched in the synovial fluid of psoriatic arthritis patients." (PMID 28163705, 2016). "As proof of concept, recent data has been published demonstrating the efficacy of IL-17A inhibition in the treatment of psoriatic arthritis." (PMID 27660709, 2016). "Secukinumab (AIN457, Novartis) a fully human anti-interleukin-17A antibody was evaluated in 18 patients with psoriatic arthritis." (PMID 23209897, 2012). "Moreover, IL-17A inhibitors demonstrated a more favorable efficacy in treating psoriatic arthritis than pustular psoriasis." (PMID 39219794, 2024). "This study aimed to examine the changes in biomarker levels in responders and non-responders to tumor necrosis factor alpha inhibitor (TNFi) and interleukin-17A inhibitor (IL-17Ai) in psoriatic arthritis (PsA) patients over a 4-month period after treatment initiation." (PMID 38474247, 2024). "Finally, guselkumab was the first IL-23 inhibitor approved for psoriatic arthritis, exhibiting efficacy data comparable to IL-17A inhibitors." (PMID 37283755, 2023). "However, the first affibody-based agent named Izokibep (ABY-035), made by the company Affibody Medical AB, recently entered phase II clinical trials as an interleukin-17A inhibitor against psoriatic arthritis." (PMID 37240041, 2023). "An inflammatory marker of particular interest in this report is interleukin 17 (IL‐17A), an inflammatory cytokine, which plays a primary role in chronic inflammatory skin conditions such as psoriatic arthritis and HS and is affiliated with mast cell degranulation." (PMID 35600027, 2022). "IL-17A signaling has been identified and successfully targeted as a clinical therapy in a host of chronic inflammatory conditions including ankylosing spondylitis and psoriatic arthritis (27, –29)." (PMID 34544860, 2021).
psoriatic arthritis (continued). "For example, GWAS in ankylosing spondylitis (AS) and psoriatic arthritis (PsA) identified IL23R, IL12B, and IL17A as associated loci, facilitating the development of ustekinumab, an IL12/23 inhibitor used in PsA, and secukinumab, an IL17A inhibitor used in both AS and PsA." (PMID 33658983, 2020). "In patients with psoriatic arthritis, bimekizumab treatment neutralizes IL-17A and IL-17F greatly inhibits pro-inflammatory cytokine secretion, but IL-17A blockade in IBD patients induced high risk of severe adverse events in clinical trials, indicating a protective role of IL-17A in IBD." (PMID 32391010, 2020). "Importantly, targeting IL-17A is also effective in psoriatic arthritis, demonstrating that the psoriatic inflammation at distant sites also depends on the action of IL-17A." (PMID 32010143, 2019). "Other polymorphisms of the IL-23/IL-17A axis, such as SNPs in TRAF3IP2 that code for the adaptor Act1, a downstream target of IL-17R, which confers susceptibility to psoriatic arthritis, may be evaluated in AS." (PMID 27415816, 2016). "However, it can be expected to be unfavorable, because an upregulation of RORγt with elevated IL-17A and IL-22 levels has been proposed to play a role in immune disorders such as severe allergic asthma, psoriatic arthritis and UV-radiation induced promotion of skin cancer." (PMID 35337918, 2022). "However, the pro-inflammatory qualities of these cytokines have made them important in the pathology of several chronic autoimmune and fibrotic inflammatory diseases, including psoriatic arthritis and ankylosing spondylitis, in which antibodies against IL-17A have revolutionised disease treatment." (PMID 35004653, 2021). "From these findings, the combined blocking of TNF-α and IL-17A may represent a new option for controlling inflammatory bone disorders as in RA, psoriatic arthritis as well as in ankylosing spondylitis and inflammatory subsets of OA and even common osteoporosis." (PMID 25904914, 2015). "In psoriatic arthritis, synovial fluid is enriched for CD69+CD103+CD8+ TRM cells that secrete IFN-γ and TNF-α and, together with IL-17A, induce cartilage-degrading enzymes, thereby directly promoting cartilage destruction." (PMID 41462958, 2025). "This case highlights the therapeutic potential of combining secukinumab (IL-17A inhibitor) and apremilast (PDE-4 inhibitor) in managing refractory chronic plaque psoriasis with psoriatic arthritis." (PMID 41393637, 2025). "Bimekizumab is the first dual targeting IL‐17A/F antibody, and the 16‐week American College of Rheumatology 50% improvement rate (ACR50) in TNF‐α inhibitor‐refractory psoriatic arthritis was 46% in one study." (PMID 40529617, 2025). "The authors indicated that IL-17A, which is produced in the skin, induces joint manifestations via FGF7 signaling in the pathology of psoriatic arthritis." (PMID 39919800, 2025). "The difference in the results for IL-17A and IL-17F can be used as a basis for distinguishing JIA from psoriatic arthritis, in which both blood cytokine levels are elevated." (PMID 38255240, 2024). "Secukinumab is a selective IL-17A inhibitor that has been approved for PSO, Psoriatic Arthritis (PsA) in adults and children." (PMID 38482003, 2024). "Bimekizumab can effectively and selectively inhibit IL-17A and IL-17F, being currently in the phase III clinical trial stage for the treatment of various inflammatory diseases, including plaque psoriasis, psoriatic arthritis." (PMID 37304306, 2023). "The pathogenesis of psoriatic arthritis is related to the innate and adaptive immune response involving different proinflammatory cytokine, including TNF, IL-1β, IL-6, IL-22, IL-23, IL-17A, and IL-18." (PMID 36297574, 2022). "Upregulation of RORγt and elevated levels of IL-17A and IL-22 producing tissue-resident memory CD8 positive T cells have been observed in skin from patients with psoriatic arthritis." (PMID 35337918, 2022).
psoriatic arthritis (continued). "Ixekizumab, another IL-17A inhibitor, was assessed in the SPIRIT-P1 phase 3 clinical trial in biologic DMARD-naïve patients with active psoriatic arthritis." (PMID 31485194, 2019). "In psoriatic arthritis, CD69+CD103+CD8+ TRM cells are enriched in synovial fluid and secrete high levels of IL-17A, indicating their involvement in local inflammation and disease relapse; Similarly, in autoimmune hepatitis, hepatic CD8+ TRM cell abundance correlates positively with disease severity." (PMID 41462958, 2025). "Both conventional and unconventional IL-17A+ CD8+ T-cells were able to induce pro-inflammatory IL-6 and IL-8 production by synovial fibroblasts from patients with psoriatic arthritis, which was reduced upon addition of anti-TNFα and anti-IL-17A neutralizing antibodies." (PMID 37367825, 2023). "Netakimab is an anti-IL-17A monoclonal antibody recommended for treatment of moderate-to-severe plaque psoriasis, ankylosing spondylitis (ClinicalTrials.gov: NCT03447704) and psoriatic arthritis (ClinicalTrials.gov: NCT03598751)." (PMID 36001576, 2022). "Bimekizumab, a human anti-IL-17 drug that inhibits both IL-17A and IL-17F, induced convincing clinical improvements in psoriatic patients with or without psoriatic arthritis." (PMID 34975883, 2021). "Finally, topical treatment with calcipotriol decreases the frequency of IL-17A+ CD8+ cells in psoriatic lesions, which is interesting in light of the correlations between these cells and disease activity in psoriatic arthritis." (PMID 28163705, 2016). "Secukinumab (SEC) is a recombinant human monoclonal antibody against interleukin-17A (IL17A) that has been approved since 2015 by the European Medicines Agency (EMA) and 2016 by the US Food and Drug Administration (FDA), for the treatment of psoriatic arthritis (PsA)." (PMID 32637422, 2020). "Secukinumab is suitable for the treatment of psoriasis and psoriatic arthritis in adults who have had an inadequate response to conventional synthetic DMARDs, and for treating axial spondyloarthritis, including AS and nonradiographic axial spondyloarthritis by targeting IL17A." (PMID 40529617, 2025).